ZNF454 (zinc finger protein 454)
Description:
May be involved in transcriptional regulation.
Synonyms: FLJ37444
Tractability: PROTAC: ubiquitination databases record sites on it.
Gene: Protein-coding gene on chromosome 5 (178,940,827 to 178,966,648, forward strand). Ensembl gene ENSG00000178187.
Subcellular location: Nucleus
Pathways (Reactome):
Gene expression (Transcription): Generic Transcription Pathway; Regulation of endogenous retroelements by KRAB-ZFP proteins
Gene Ontology:
Molecular function: sequence-specific double-stranded DNA binding; DNA-binding transcription factor activity, RNA polymerase II-specific; RNA polymerase II cis-regulatory region sequence-specific DNA binding
Biological process: regulation of transcription by RNA polymerase II; regulation of DNA-templated transcription
Cellular component: nucleus
Genetic constraint (gnomAD): Loss-of-function variants: 28 observed, 48.77 expected, observed/expected ratio (o/e) 0.57, 90% interval 0.42 to 0.79. The upper end of that interval is the gene's LOEUF score, 0.79, which puts it in group 3 of 6, group 1 being the genes least tolerant of losing a copy. Missense variants: 509 observed, 653.73 expected, observed/expected ratio (o/e) 0.78, 90% interval 0.72 to 0.84. Synonymous variants: 204 observed, 223.04 expected, observed/expected ratio (o/e) 0.91, 90% interval 0.81 to 1.03.
Homologues: Orthologues: chimpanzee ZNF454 (99% identical), pig ZNF454 (88% identical), dog ZNF454 (84% identical), rabbit ZNF454 (82% identical), mouse Zfp454 (80% identical), rat Zfp454 (77% identical). Paralogues in human: ZNF879 (50% identical), ZNF568 (49% identical), ZNF726 (48% identical), ZNF7 (48% identical), ZNF471 (48% identical), ZNF595 (48% identical), ZNF724 (48% identical), ZNF33B (48% identical), ZNF429 (48% identical), ZNF658 (48% identical), ZNF250 (48% identical), ZFP28 (47% identical), and 164 more.
Diseases named in the same sentence as ZNF454 in open-access papers:
ZNF454 is named in the same sentence as 6 diseases in open-access papers, as found by Europe PMC text mining. Sharing a sentence is not in itself a finding about the gene and the disease. The quoted sentences say what the papers report.
endometrioid carcinoma (1 paper, 2022). "However, ZNF454 had a significant difference between endometrioid carcinoma and serous carcinoma (P < 0.001) and between serous carcinoma and mixed carcinoma (P < 0.05)." (PMID 35574348, 2022).
lung carcinoma (1 paper, 2024). "A linear model was then constructed with the expression of ZNF454 as the dependent variable and the methylation of SETDB1 binding motif and/or the expression level of SETDB1 as the independent variables using our lung cancer data." (PMID 38544480, 2024).
cancer (2 papers, 2022 to 2025). A tumor composed of atypical neoplastic, often pleomorphic cells that invade other tissues. "Two hypermethylated genes, namely, cysteine dioxygenase type 1 (CDO1) and zinc finger protein 454 (ZNF454), in patients with EC were identified from The Cancer Genome Atlas database." (PMID 35574348, 2022).
tumor (2 papers, 2022 to 2024). "It is noteworthy that the negative correlation between methylation of SETDB1 motifs and ZNF454 expression was also stronger in tumor samples (r = −0.66, p‐value = 4.8e‐08) compared to normal samples (r = −0.37, p‐value = 5.97e‐03)." (PMID 38544480, 2024). "ZNF454 may be a tumor-suppressor gene with potential use as a prognostic indicator, but its methylation site was not previously reported in EC." (PMID 35574348, 2022). "However, the positive correlation between the expression of ZNF454 and STEDB1 was more pronounced in normal (r = 0.75, p‐value = 4.6e‐02) than tumor (r = 0.27, p‐value = 5.1e‐03) samples." (PMID 38544480, 2024).
ZNF454 also shares sentences with these, for which no sentence is quoted: endometrial cancer (1 paper); serous carcinoma (1).